ATP2B3 (ATPase plasma membrane Ca2+ transporting 3)
Description:
ATP-driven Ca(2+) ion pump involved in the maintenance of basal intracellular Ca(2+) levels at the presynaptic terminals. Uses ATP as an energy source to transport cytosolic Ca(2+) ions across the plasma membrane to the extracellular compartment. May counter-transport protons, but the mechanism and the stoichiometry of this Ca(2+)/H(+) exchange remains to be established (By similarity).
Synonyms: PMCA3; CFAP39; CLA2; OPCA; PMCA3a; SCAX1
Tractability: Small molecule: it belongs to a druggable protein family. Antibody: UniProt places it where antibodies can reach, with high confidence; its Gene Ontology location is reachable by antibodies, with high confidence; UniProt predicts a signal peptide or a membrane-spanning region. PROTAC: ubiquitination databases record sites on it; its protein half-life has been measured.
Gene: Protein-coding gene on chromosome X (153,517,637 to 153,582,939, forward strand). Ensembl gene ENSG00000067842.
Subcellular location: Cell membrane; Presynaptic cell membrane
Subcellular location (Human Protein Atlas): Nucleoplasm; Plasma membrane
Pathways (Reactome):
Hemostasis: Reduction of cytosolic Ca++ levels
Muscle contraction: Ion homeostasis
Transport of small molecules: Ion transport by P-type ATPases
Gene Ontology:
Molecular function: calcium ion transmembrane transporter activity; P-type calcium transporter activity involved in regulation of presynaptic cytosolic calcium ion concentration; protein binding; P-type calcium transporter activity; ATP binding; ATP hydrolysis activity; nucleotide binding
Biological process: calcium ion export across plasma membrane; regulation of cytosolic calcium ion concentration; monoatomic ion transmembrane transport; regulation of cardiac conduction; calcium ion transmembrane transport; regulation of presynaptic cytosolic calcium ion concentration
Cellular component: extracellular vesicle; GABA-ergic synapse; glutamatergic synapse; plasma membrane; parallel fiber; parallel fiber to Purkinje cell synapse; presynaptic membrane; membrane
Cancer hallmarks: suppression of growth (promotes)
Homologues: Orthologues: chimpanzee ATP2B3 (100% identical), macaque ATP2B3 (99% identical), mouse Atp2b3 (98% identical), rat Atp2b3 (98% identical), guinea pig ATP2B3 (98% identical), dog ATP2B3 (97% identical), rabbit ATP2B3 (95% identical), pig ATP2B3 (94% identical), tropical clawed frog atp2b3 (88% identical), Drosophila melanogaster SPoCk (22% identical), Caenorhabditis elegans pmr-1 (20% identical), Caenorhabditis elegans catp-2 (19% identical), and 4 more. Paralogues in human: ATP2B2 (84% identical), ATP2B1 (80% identical), ATP2B4 (75% identical), ATP2A2 (25% identical), ATP1A1 (25% identical), ATP2A3 (24% identical), ATP1A2 (24% identical), ATP1A3 (24% identical), ATP2A1 (24% identical), ATP1A4 (24% identical), ATP12A (23% identical), ATP2C1 (23% identical), and 9 more.
Diseases named in the same sentence as ATP2B3 in open-access papers:
ATP2B3 is named in the same sentence as 46 diseases in open-access papers, as found by Europe PMC text mining. Sharing a sentence is not in itself a finding about the gene and the disease. The quoted sentences say what the papers report.
adenoma (10 papers, 2015 to 2025). A neoplasm arising from the epithelium. "The mutations of ATP1A1 (such as p.Leu104Arg) are also predominantly found in adenomas with cells resembling the ZG (i.e., in ZG-like APAs), as are the ATP2B3 aldosterone-driving mutations." (PMID 40725432, 2025). "In the last decade, somatic pathogenic variants in KCNJ5, CACNA1D, ATP1A1 and ATP2B3 genes, which are involved in maintaining intracellular ionic homeostasis and cell membrane potential, were described in aldosterone-producing adenomas (aldosteronomas)." (PMID 35813615, 2022). "This classical adenoma harbored a novel ATP2B3 K416_F418delinsN somatic mutation, which is a deletion from nucleotides 1248 to 1253." (PMID 34572956, 2021). "Moreover, we have used Sanger sequencing to confirm that there were no other conventional and well-characterized aldosterone-driving gene mutations, including KCNJ5, ATP1A1, CACNA1D, and CTNNB1, in the adenoma harboring with ATP2B3 K416_F418delinsN mutation." (PMID 34572956, 2021). "Based on our tissue bank of aldosterone-producing adenomas (APA), we identified a novel somatic ATP2B3 K416_F418delinsN mutation." (PMID 34572956, 2021). "Several somatic mutations have been found in aldosterone-producing adenomas in KCNJ5, ATP1A1, ATP2B3, CACNA1D, and CTNNB1 genes." (PMID 32783015, 2020). "Adenomas with CTNNB1 mutations showed a large number of differentially expressed genes (1360 compared to 106 and 75 for KCNJ5 and ATP1A1/ATP2B3 respectively) and clustered together in a hierarchical clustering analysis." (PMID 31000732, 2019). "Several lines of evidence suggest that KCNJ5-mutant aldosterone-producing adenomas have distinct clinicopathological phenotype compared to those harboring ATP1A1, ATP2B3, and CACNA1D mutations." (PMID 29594118, 2018). "Targeted sequencing for the reported mutations in APAs of KCNJ5, CACNA1D, ATP1A1, ATP2B3 and CTNNB1 exons was performed from the adenomas." (PMID 28102204, 2017). "At the molecular level, somatic mutations involving potassium channels (KCNJ5), ATPases (ATP1A1 and ATP2B3), and calcium channels (CACNA1D) account for approximately 60% of sporadic aldosterone-producing adenomas." (PMID 29594118, 2018). "In contrast, tumors that are composed predominantly of ZG-like compact cells are typically enriched in ATP1A1-, ATP2B3-, and CACNA1D-mutant aldosterone-producing adenomas that show increased and strong CYP11B2 expression and predominantly negative CYP11B1 or CYP17A1 expression profiles." (PMID 29594118, 2018).
Ataxia (9 papers, 2014 to 2025). Ataxia refers to impaired coordination of voluntary muscle movement. "The missense mutation G1107D in ATP2B3 has been identified in patients with X-linked congenital cerebellar ataxia." (PMID 37374132, 2023). "In humans, genetic mutations in ATP2B1, ATP2B2 and ATP2B3 gene have been linked with hearing loss, cerebellar ataxia and global neurodevelopmental delay: all of them were found to impair pump activity." (PMID 36207321, 2022). "In the present study, we describe three different ATP2B3 novel missense mutations potentially associated with patient’s clinical phenotype compatible with cerebellar ataxia." (PMID 36207321, 2022). "Cali and colleagues identified another mutation in ATP2B3 gene in a patient with cerebellar ataxia and global developmental delay." (PMID 33801794, 2021). "Although the phenotype reported is similar to that seen in other families, this is the only reported ATP2B3 ataxia mutation to date." (PMID 25055202, 2014). "The link between ataxia and PMCA3 became evident when Zanni and coworkers identified a point mutations in ATP2B3 gene (located on the human chromosome X) in a family affected by X-linked congenital cerebellar ataxia." (PMID 33801794, 2021). "A mutation in ATP2B3, also known as PMCA3, was recently associated with spinocerebellar ataxia in an Italian family." (PMID 25055202, 2014).
adrenocortical adenomas (4 papers, 2018 to 2025). "Outside neurology, ATP2B3 has been linked to aldosterone-producing adrenocortical adenomas, which are benign tumors of the adrenal cortex that secrete aldosterone autonomously and typically present with hypertension, hypokalemia, and muscle weakness." (PMID 41373895, 2025). "ATP2B3 is a causal gene in benign aldosterone-producing adrenal lesions and adrenocortical adenomas." (PMID 36875704, 2023). "In DNA samples extracted from APA tumor tissues, we identified the mutant ATP2B3 gene in a left adrenal adenoma." (PMID 34572956, 2021). "Indeed, a proportion of patients with primary aldosteronism are now known to harbor adrenal cortical adenomas with heterogeneous molecular alterations (KCNJ5, ATP1A1, ATP2B3, and CACNA1D) involving the calcium/calmodulin kinase signaling pathway." (PMID 29594118, 2018).
Hypokalemia (3 papers, 2021 to 2025). An abnormally decreased potassium concentration in the blood. "Our index patient with ATP2B3 K416_F418delinsN had uncontrollable hypertension and hypokalemia at presentation." (PMID 34572956, 2021).
primary aldosteronism (2 papers, 2018 to 2021). An endocrine disorder characterized by excessive production of aldosterone by the adrenal glands. "The ATP2B3 channel mutation is a rare cause of primary aldosteronism (PA)." (PMID 34572956, 2021). "In patients with primary aldosteronism (PA), the prevalence of ATP2B3 mutation is rare." (PMID 34572956, 2021). "Several studies have confirmed the tumorigenic role of this mutation as it was mutually exclusive to ion channel-related (KCNJ5, ATP1A1, ATP2B3, and CACNA1D) mutations in primary aldosteronism." (PMID 29594118, 2018).
aldosteronomas (1 paper, 2022). "Aldosteronomas are a major cause of unilateral PA, associated with somatic variants in KCNJ5, CACNA1D, ATP1A1, ATP2B3, CLCN2, CACNA1H and CTNNB1 genes." (PMID 35813615, 2022).
attention deficit-hyperactivity disorder (1 paper, 2018). A disorder characterized by a marked pattern of inattention and/or hyperactivity-impulsivity that is inconsistent with developmental level and clearly interferes with functioning in at least two settings (e.g. at home and at school). "Additionally, six genes displaying at least differential expression among hemispheres (BAIAP2, DAPPER1, LMO4, NEUROD6, ATP2B3, and ID2) in a case-control association study in an initial Spanish sample of ADHD (Attention Deficit Hyperactivity Disorder) patients and control subjects." (PMID 30081481, 2018).
colitis (1 paper, 2022). Inflammation of the colon. "Western blot analysis of the colon samples confirmed a reduction in plasm membrane Ca2+ pump proteins (PMCA), encoded by Atp2b1, Atp2b2, Atp2b3, and Atp2b4 and recognized by the same antibody, in colitis mice, which was rescued by BBR." (PMID 36528592, 2022).
COVID-19 (1 paper, 2024). A disease caused by infection with severe acute respiratory syndrome coronavirus 2. "Furthermore, there were undetectable expression levels of ATP2A1, ATP2A3, ATP2B2, and ATP2B3 in the lungs of both COVID-19 patients and controls (Fig. EV1G)." (PMID 38816514, 2024).
diabetes (1 paper, 2013). "In the diabetic sternohyoid, three of the five calcium channel genes with decreased expression (Fstl1, Atp2b3, Eef2k, Gpd2, Myl6b) were decreased in previous diabetes studies." (PMID 24199937, 2013).
familial hyperaldosteronism (1 paper, 2021). "Somatic mutations in four genes (KCNJ5, ATP1A1, ATP2B3 and CACNA1D) have been identified in nearly 60% of the sporadic APAs, while germline mutations in KCNJ5 and CACNA1H have been reported in different subtypes of familial hyperaldosteronism." (PMID 34829937, 2021).
Gait ataxia (1 paper, 2023). A type of ataxia characterized by the impairment of the ability to coordinate the movements required for normal walking. "The most condition related to the ATP2B3 gene is X-linked Cerebellar ataxia-1 (SCAX1, OMIM: 302,500), an X-linked recessive neurologic disorder characterized by hypotonia at birth, delayed motor development, gait ataxia, difficulty standing, dysarthria, and slow eye movements." (PMID 37821930, 2023).
hepatoma (1 paper, 2021). "Regarding the less abundant isoforms, Atp2b2 showed a significant decrease in tumor cells, while Atp2b3 showed an increasing but not significant trend in hepatoma cells." (PMID 34737944, 2021).
X-linked spinocerebellar ataxia (1 paper, 2021). "The 105 kb microduplication at Xq28 also included the ATP2B3, whose mutations were associated with X-linked spinocerebellar ataxia." (PMID 34659328, 2021). "Furthermore, the 125 kb microduplication at Xq28 encompassed the ATP2B3 associated with X-linked spinocerebellar ataxia." (PMID 34659328, 2021).
tumor (8 papers, 2014 to 2022). "Somatic mutations in KCNJ5, ATP1A1, ATP2B3, CACNA1D and CTNNB1 have been described in ~60% of these tumours." (PMID 31000732, 2019). "For example, elevating cytosolic calcium through inhibiting ATP2B3 or activating the voltage-dependent calcium channels in macrophages might start M1-like polarization and enhance anti-tumor immunity." (PMID 36536301, 2022). "In the fifteen tumours subjected to RNA-Sequencing in this study, opposite patterns of expression in tumours with mutations in KCNJ5 and those with mutations in CACNA1D/ATP1A1/ATP2B3 were observed, with KCNJ5-mutants showing higher levels of CYP11B1 expression and lower levels of CYP11B2 expression." (PMID 31000732, 2019).
cancer (5 papers, 2015 to 2023). A tumor composed of atypical neoplastic, often pleomorphic cells that invade other tissues. "When we limited the analysis to the genes of the COSMIC Cancer Gene Census Tier 1, only four genes, including ATP2B3, CACNA1D, KRAS, and PIK3CA, showed recurrent mutations only in two patients." (PMID 37920164, 2023). "Several previous studies support the findings of the present study, including the link between ATP2B2 and ATP2A3 in cancer, as well as the hypothesis that ATP2B3 might serve as a possible cancer biomarker." (PMID 34684111, 2021). "Thus, while its expression synergisms with the ATP2B3 (ATPase, Ca++ transporting, plasma membrane 3) and KLK2 (kallikrein-related peptidase 2) in NOR are not modified by ccRCC, the antagonistic expression with the AP2A1 is switched to a synergistic one in all three cancer nodules." (PMID 38132440, 2023).
neurological disease (4 papers, 2016 to 2023). "We also demonstrate the inhibitory effect of ATP2B3 knockdown on the P62−KEAP1−NRF2−HO-1 signaling pathway, which has potential implications for the treatment of neurological diseases." (PMID 37298147, 2023).
myopathies (1 paper, 2020). "Although hyper-methylation-induced RyR1 silencing was unveiled in skeletal muscle of patients with recessive core myopathies, our knowledge concerning the epigenetic regulation in RyR1-mediated adipogenesis and myogenesis within skeletal muscle remains limited, let alone ATP2B3." (PMID 33308295, 2020).
skeletal dysplasia (1 paper, 2024). Any Mendelian diseases that affects growth and development of the skeleton. "A distinct clinical feature, specifically mild skeletal dysplasia, was observed in males carrying a partial deletion of BGN and the 5’-UTR of the neighboring ATP2B3, compared to males with other loss-of-function BGN variants." (PMID 38531898, 2024).
ATP2B3 also shares sentences with these, for which no sentence is quoted: cerebellar ataxia (4 papers); infection (3); X-linked cerebellar ataxia (3); adrenocortical tumors (2); Huntington disease (2); Hypertension (2); neurodegenerative disease (2); acquired ataxia (1); adrenal tumor (1); Alzheimer disease (1); Arthritis (1); ataxic disorders (1); Boucher–Neuhauser Syndrome (1); cerebellar degeneration (1); Cerebellar dysplasia (1); dementia (1); genetic diseases (1); hearing loss (1); hemophagocytic lymphohistiocytosis (1); meningitis (1); multiple sclerosis (1); Obesity (1); Parkinson disease (1); pheochromocytoma (1); rheumatoid arthritis (1); Sepsis (1); type 2 diabetes mellitus (1).